HMGB1 (high mobility group box 1)
Diseases named in the same sentence as HMGB1 in open-access papers (continued):
Sharing a sentence is not in itself a finding about the gene and the disease.
cholesteatoma (continued). "Based on our previous and current results from ex vivo and in vitro studies, we hypothesize that the increased level of HMGB1 in sEVs in patients with acquired cholesteatoma may be a new and key factor involved in disease progression." (PMID 37998605, 2023). "Moreover, it was demonstrated that the expression of extracellular HMGB1 and DNA fragments in cholesteatoma keratinocytes induce the production of TNF-α and IL-1β, which leads to bone resorption and destruction associated with cholesteatoma." (PMID 37998605, 2023). "Interestingly, the DAMPs HMGB1 and Tenascin are also suspected to contribute to cholesteatoma pathogenesis." (PMID 33627146, 2021). "Although the distribution of HMGB1 in relation to wound healing has been observed in human skin and cholesteatoma, studies dealing with palatal wound healing and the target mutation of Hmgb1 gene in vivo have not been previously performed." (PMID 27886093, 2016). "This might result in molecular changes such as apoptosis or hypoxia and necrotic cell death within the cholesteatoma tissue, followed by release of HMGB1." (PMID 25385222, 2015). "It is also plausible that RAGE/HMGB1 interactions may trigger the signaling pathways involved in the regulation of chronic inflammation as well as bone resorption in cholesteatoma." (PMID 25385222, 2015). "The cholesteatoma molecular pathogenesis, growth, and inflammation might be related to the co-expression and functional interactions between HMGB1 and RAGE." (PMID 25385222, 2015). "These correlations may indicate a role for HMGB1 in the formation and development of cholesteatoma." (PMID 37998605, 2023). "Thus, HMGB1(+) sEVs emerge as a novel factor potentially promoting cholesteatoma progression." (PMID 37998605, 2023). "The presence of epithelium in paraffin sections of normal skin and cholesteatoma tissues was the requirement for evaluating RAGE and HMGB1 expression." (PMID 25385222, 2015). "The authors proposed that HMGB1 and RAGE overexpression in cholesteatoma promotes increased keratinocyte proliferation, survival, and migration via the activation of the PI3K/Akt/NF-κB, MAPK p44/p42, Erk1/2, and STAT3 signaling pathways, while also enhancing IL-8 release." (PMID 39769332, 2024). "In our previous studies, we found increased expression of HMGB1 and RAGE in cholesteatoma tissue." (PMID 37998605, 2023). "The hypothesis was tested that receptor for advanced glycation endproduct (RAGE) and its ligand, high-mobility box 1 (HMGB1), are overexpressed in cholesteatoma, and the RAGE/HMGB1 axis might contribute to its pathogenesis." (PMID 25385222, 2015). "Most likely, it is HMGB1 which triggers paracrine activation of RAGE expressed in the cholesteatoma matrix but not (or only weakly) in normal skin." (PMID 25385222, 2015). "The role of RAGE/HMGB1 interactions in bone remodeling has been reviewed, and a higher expression of RAGE within cholesteatoma perimatrix, which is adjacent to ossicle surface or to other parts of the temporal bone, might be interpreted as indicative of the RAGE/HMGB1 involvement in this process." (PMID 25385222, 2015). "Thus, its overexpression and potential involvement in molecular signaling are not specific to cholesteatoma but are manifestations of the inflammatory cascade that HMGB1 sustains via the HMGB1/RAGE axis." (PMID 25385222, 2015).
chronic hepatitis (7 papers, 2010 to 2023). An active inflammatory process affecting the liver for more than six months. "Another two studies investigated the serum HMGB1 levels, suggesting there were higher serum HMGB1 levels in patients with chronic hepatitis than in healthy people (p<0.01 and p<0.05 respectively)." (PMID 25356587, 2014). "Two additional studies showed that there were higher serum HMGB1 levels in patients with chronic hepatitis than those in healthy people (p<0.05)." (PMID 25356587, 2014). "Significantly higher serum HMGB1 was detected in the patients with chronic hepatitis compared to those detected in healthy people." (PMID 25356587, 2014). "This compound is the first to be reported to target HMGB1 in chronic hepatitis." (PMID 36895013, 2023). "Interestingly, two studies investigated serum HMGB1 in patients with chronic hepatitis (the precursor of HCC) and healthy people." (PMID 25356587, 2014).
Disseminated intravascular coagulation (7 papers, 2007 to 2022). Disseminated intravascular coagulation is characterized by the widespread activation of coagulation, which results in the intravascular formation of fibrin and ultimately thrombotic occlusion of small and midsize vessels. "Mean levels of HMGB1 were as follows: undetectable in healthy controls, 4.54 ng/ml in infected patients, 2.15 ng/ml in patients with malignant disease, 6.47 ng/ml in trauma patients, and 14.05 ng/ml in patients with disseminated intravascular coagulation." (PMID 17346334, 2007). "Histone H3 but not HMGB1 levels were positively correlated with surgical time, the Sequential Organ Failure Assessment score, the Japanese Association for Acute Medicine acute phase disseminated intravascular coagulation diagnosis score, and the length of ICU stay." (PMID 37234401, 2022).
experimental autoimmune encephalomyelitis (7 papers, 2018 to 2022). An autoimmune demyelinating disease of the central nervous system that is produced experimentally in animals by the injection of homogenized brain or spinal cord in Freund's adjuvant. "Thorough analysis of EP's mechanism of action in the autoimmune process that targets CNS suggests that EP ameliorated the symptoms of experimental autoimmune encephalomyelitis through inhibition of HMGB1 secretion from microglia/macrophages." (PMID 30687329, 2018).
hepatitis B (7 papers, 2011 to 2025). "In ALF patients caused by hepatitis B, the HMGB1 translocation rates were around 32.84% ± 7.13%, which was significantly higher than that in chronic hepatitis B patients and controls." (PMID 21406085, 2011). "Immunohistochemical staining was performed to confirm the expression and subcellular localization of HMGB1 in liver specimens obtained from 13 patients with ACLF caused by hepatitis B virus (HBV) infection, 20 patients with chronic viral hepatitis B and 20 healthy controls." (PMID 25187820, 2014). "A meta-analysis also indicates that HMGB1 may be a useful therapeutic target for severe hepatitis B and ACLF." (PMID 34904016, 2021). "It has also been administered to patients with hepatitis B and C and is considered to be safe for human consumption, but GL may have off-target effects other than inhibition of HMGB1." (PMID 31560698, 2019).
juvenile idiopathic arthritis (7 papers, 2014 to 2022). Juvenile idiopathic arthritis (JIA) is the term used to describe a group of inflammatory articular disorders of unknown cause that begin before the age of 16 and last over 6 weeks. "Several studies demonstrated a correlation between the presence of the disulfide HMGB1 and the onset of pathologies such as brain injury, liver damage, myositis, and juvenile idiopathic arthritis." (PMID 26347745, 2015). "The HMGB1 inside the cell (nucleus or cytosol) is completely reduced, and early prevalence of fully reduced HMGB1 and subsequenct appearance of disulfide HMGB1 were observed in models of brain, muscle, or liver injuries and in patients with Juvenile Idiopathic Arthritis." (PMID 26347745, 2015). "The role of the immune response in juvenile idiopathic arthritis (JIA) is self‐evident, and research on HMGB1 in JIA has occurred for more time than that in other pediatric diseases." (PMID 33140586, 2021). "In a study on 116 children suffering either from SLE or juvenile idiopathic arthritis (JIA), all patients showed significantly higher HMGB1 serum levels and significantly lower sRAGE serum levels when compared to 27 healthy controls." (PMID 26854151, 2015). "In support of that, also AGEs and HMGB1 accumulated and correlated positively with disease course and manifestation, while circulating sRAGE concentrations were found to be decreased in patients with RA, SLE and juvenile idiopathic arthritis." (PMID 31266174, 2019).
Kawasaki disease (7 papers, 2014 to 2026). A rare inflammatory disease characterized by an acute febrile, systemic, self-limiting, medium-vessel vasculitis primarily affecting children. "The purpose of our study was to verify the mechanism and clinical significance of HMGB1-RAGE in coronary artery injury of Kawasaki disease." (PMID 32183905, 2020). "Increased plasma levels of HMGB1 have been shown in the acute phase of Kawasaki disease." (PMID 38275751, 2023). "HMGB1 is reported to induce signalling via the RAGE receptor and the HMGB1/RAGE/cathepsin B signalling pathway, which activates NLRP3-dependent coronary endothelial cell pyroptosis and thus plays an important role in the endothelial damage that occurs in Kawasaki disease." (PMID 32795339, 2020).
keloid (7 papers, 2017 to 2025). An irregularly shaped, elevated mark on the skin caused by deposits of excessive amounts of collagen during wound healing. "In this study, we investigated the role of HMGB1 in skin fibrosis and keloid scar formation and its underlying mechanism." (PMID 29849053, 2018). "There are several mechanisms by which HMGB1 promotes the fibroblast proliferation associated with keloid development." (PMID 29283384, 2017). "Unlike previous studies, which showed increased or decreased expression levels of HMGB1 under certain conditions, our study focused on the molecular signaling pathways associated with keloid development." (PMID 29283384, 2017). "As extranuclear HMGB1 promotes cell survival under stressed conditions by inducing autophagy, we sought to determine whether HMGB1 is associated with keloid pathogenesis through regulation of the cellular death process." (PMID 31450620, 2019). "Our study further demonstrates that HMGB1 may induce the fibroproliferative properties associated with excessive collagen accumulation, as observed in keloid tissue." (PMID 29283384, 2017). "Therefore, we speculated that HMGB1 is associated with aberrant cellular death in keloids that exhibit attenuated apoptotic activity." (PMID 31450620, 2019). "Therefore, we hypothesized that HMGB1, a well-known initiator of inflammation, might be associated with normal dermal fibrosis and keloid, as is TGF-β." (PMID 29849053, 2018). "High-mobility group box 1 (HMGB1) drives keloid pathogenesis by enhancing fibroblast proliferation, collagen synthesis, and myofibroblast differentiation, primarily through activation of RAGE-MAPK, NF-κB, and AKT signaling." (PMID 41424791, 2025). "Glycyrrhizin, a licorice-derived compound, inhibits HMGB1, a key mediator of inflammation, fibrosis, and autophagy in keloids." (PMID 41424791, 2025). "Studies have shown HMGB1’s abundance in keloid tissues and its role in inducing fibrosis through TGF-β1, Erk 1/2, Akt, and NF-κB pathways." (PMID 38892032, 2024). "Treatment with lipopolysaccharide (LPS) induced inflammation in fibroblasts, resulting in keloid formation through the activation of HMGB1." (PMID 38892032, 2024). "In our previous study, LPS-induced inflammation in fibroblasts increased the activation of HMGB1, subsequently increasing keloid formation through the Erk1/2, Akt, and NF-κB signaling pathways." (PMID 38892032, 2024). "In particular, a high-magnification view showed that HMGB1 was abundantly expressed in the cytosol and extracellular space of keloid tissue (400× magnification)." (PMID 31450620, 2019). "IHC of HMGB1 revealed that the expression of HMGB1 was significantly increased in the keloid tissue compared with that in normal dermis (* p < 0.05)." (PMID 31450620, 2019). "Inhibition of HMGB1 with glycyrrhizin decreased fibrosis, increased apoptosis, and diminished autophagy in keloids." (PMID 31450620, 2019). "In this study, we explored the possible involvement of autophagy and HMGB1 as a cell death regulator in keloid pathogenesis." (PMID 31450620, 2019). "Subsequently, we inhibited HMGB1 activity and observed changes in cell death and factors related to fibrogenesis in keloids." (PMID 31450620, 2019). "In this study, we focused on the autophagy of keloids in regulating fibrogenesis, along with possible involvement of HMGB1." (PMID 31450620, 2019). "Here, we showed that glycyrrhizin attenuated HMGB1 expression and suppressed mitogenic activity in keloids." (PMID 31450620, 2019). "If HMGB1 promotes autophagy in keloids, then inhibition of HMGB1 should reduce the cellular viability of keloids." (PMID 31450620, 2019). "HMGB1 and its effector toll-like receptors and receptors for advanced glycation end product proteins are actively expressed in keloid tissues." (PMID 29849053, 2018).
keloid (continued). "In the current study, we investigated the translocation and active release of HMGB1 from normal dermal fibroblasts during LPS stimulation, and the redistribution of nuclear HMGB1 into the cytoplasm of keloid fibroblasts." (PMID 29849053, 2018). "We investigated the translocation and active release of HMGB1 from normal dermal fibroblasts under lipopolysaccharide stimuli, and the redistribution of nuclear HMGB1 into the cytoplasm of keloid fibroblasts." (PMID 29849053, 2018). "The present study was designed to evaluate the role of HMGB1 in the development of keloids by conducting an in vitro assay to uncover its mechanism of action in normal and keloid fibroblasts." (PMID 29283384, 2017). "The results of this study demonstrated that HMGB1 alters the behavior of both normal and keloid fibroblasts." (PMID 29283384, 2017). "Treatment with HMGB1 promoted an increase in the migration of both normal and keloid fibroblasts to a degree equivalent to that achieved by treatment with TGF-β." (PMID 29283384, 2017). "HMGB1 promoted both normal and keloid fibroblasts migration to a degree equivalent to that achieved with TGF-β." (PMID 29283384, 2017). "By inhibiting the cytoplasmic translocation of HMGB1, EP may protect against inflammation, pathological fibrosis, and oncogenesis, potentially disrupting keloid progression and attenuating fibrosis in keloids." (PMID 38892032, 2024). "In our previous study, we demonstrated the overexpression of HMGB1 in keloid tissue, and that cytoplasmic translocation and exogenous HMGB1 could trigger proliferation of HDFs and enhance ECM production." (PMID 38892032, 2024). "In addition, we have highlighted the potential of glycyrrhizin, a potent inhibitor of HMGB1, as a promising agent for the treatment of keloids." (PMID 31450620, 2019). "The HMGB1 blocker, glycyrrhizin, was shown to ameliorate fibrosis in keloids." (PMID 31450620, 2019). "TGF-β, Smad2/3, ERK1/2, and HMGB1 were decreased in glycyrrhizin-treated keloids." (PMID 31450620, 2019). "Accordingly, we confirmed the presence and overexpression of HMGB1 in keloid tissues." (PMID 31450620, 2019). "Higher HMGB1 expression and enhanced autophagy were observed in keloids." (PMID 31450620, 2019). "In this study, we attempted to determine whether the pathological dermal fibrosis seen in keloid and hypertrophic scars resulted from excess HMGB1." (PMID 29849053, 2018). "Our results strongly suggest that HMGB1 could be an effective therapeutic target for treating abnormal dermal fibroses such as keloid and hypertrophic scars." (PMID 29849053, 2018). "In conclusion, the results of this study show that endogenous HMGB1 may be an essential profibrogenic molecule, and is a potential target for keloid tissue therapy." (PMID 29849053, 2018). "We determined whether HMGB1 plays a role in normal dermal fibrosis and keloid, and is involved with transforming growth factor β." (PMID 29849053, 2018). "However, there is scanty information on the relationship between skin fibrosis and HMGB1, especially in keloid." (PMID 29849053, 2018). "We expect that further knowledge of the relationship of skin fibrosis to HMGB1 may help to develop a new clinical approach to treat and prevent keloids and hypertrophic scars." (PMID 29283384, 2017). "In a previous study, we demonstrated that HMGB1 induces the expression of EMT-associated proteins in normal fibroblasts; thus, we hypothesized that inhibiting HMGB1 activity or its related signals could be beneficial for treating or even preventing keloids." (PMID 29283384, 2017). "Furthermore, HMGB1-induced increases in the motility of normal and keloid fibroblasts were significantly inhibited by treatment with GA." (PMID 29283384, 2017). "Consequently, inhibition of HMGB1 with glycyrrhizin may disrupt keloid progression and attenuate fibrosis in keloids." (PMID 31450620, 2019).
keloid (continued). "Inhibition of HMGB1 with glycyrrhizin reduced ECM expression and autophagy in keloids but enhanced apoptosis, thereby suggesting its potential use in keloid treatment." (PMID 36009363, 2022). "NLRP3 inflammasome is often stimulated by high mobility group box 1 (HMGB1), Toll-like receptor (TLR4), NF-κB, and reactive oxygen species known to be increased in keloid." (PMID 33126764, 2020). "Collectively, these results indicate that exogenous HMGB1 induced profibrotic signaling molecules, and glycyrrhizin modulated TGF-β and its signaling pathway, thus reducing fibrosis in keloids." (PMID 31450620, 2019). "Our previous results demonstrated that autophagy is increased in keloids, and that exogenous fibrogenic molecules, such as TGF-β and HMGB1, enhance autophagic activity in fibroblasts." (PMID 31450620, 2019). "Therefore, we assess whether glycyrrhizin could reduce HMGB1 expression in keloids in advance." (PMID 31450620, 2019). "Compared with extra-lesional normal tissue, markedly increased HMGB1, RAGE, and TLR4 immunoreactivity was noted in the central and peripheral keloid regions." (PMID 29849053, 2018). "We carried out immunohistochemical staining to investigate the expression patterns of HMGB1 and its receptors (RAGE and TLR4 proteins) in keloid tissue (n = 5)." (PMID 29849053, 2018). "We also discovered an extracellular excess of HMGB1 and an increase in the levels of the HMGB1 receptors RAGE and TLR4 in the keloid tissue compared with the adjacent normal skin." (PMID 29849053, 2018). "Although glycyrrhizin is recognized as a potent HMGB1 inhibitor, no study has investigated the effect of this compound on keloids." (PMID 31450620, 2019). "The results showed that glycyrrhizin-treated keloid spheroids showed markedly decreased HMGB1 expression, while non-treated keloid spheroids showed higher expression of HMGB1 (*** p < 0.001)." (PMID 31450620, 2019). "Although the role of HMGB1 in wound healing has been investigated, no studies to date have evaluated its role in cutaneous scarring and keloid development." (PMID 29283384, 2017). "Although there are currently no effective therapeutic interventions for keloids, small-molecule inhibitors targeting HMGB1 or its receptors based on silencing HMGB1, RAGE, or TLRs have proven successful in reducing the severity of symptoms in various experimental models of fibrotic diseases." (PMID 29283384, 2017).
Lewis lung carcinoma (7 papers, 2014 to 2022). "Recently, Korbelik and coworkers demonstrated in mice serum with Lewis Lung Carcinoma (LLC) tumors treated with Photofrin, that actively secreted and passively released HMGB1 are respectively involved during the early and late stages after treatment." (PMID 25140900, 2014). "The in vitro model of I/R, oxygen-glucose deprivation and reperfusion (OGD/R), effectively induced CRT exposure, ATP secretion, high mobility group box 1 (HMGB1) release and eIF2α phosphorylation in both Lewis lung carcinoma (LLC) and A549 cells when combined with CDDP." (PMID 36057637, 2022). "Also, ELISA was used to test the exposure levels of HMGB1, IL-10, and TGF-β under different “time windows” and “dose windows” of irradiation with X-rays and carbon ions for A549, H520, and Lewis Lung Carcinoma (LLC) cell lines." (PMID 33968889, 2021).